MYMK (myomaker, myoblast fusion factor)
Description:
Myoblast-specific protein that mediates myoblast fusion, an essential step for the formation of multi-nucleated muscle fibers. Actively participates in the membrane fusion reaction by mediating the mixing of cell membrane lipids (hemifusion) upstream of MYMX. Acts independently of MYMX (By similarity). Involved in skeletal muscle regeneration in response to injury by mediating the fusion of satellite cells, a population of muscle stem cells, with injured myofibers (By similarity). Also involved in skeletal muscle hypertrophy, probably by mediating the fusion of satellite cells with myofibers (By similarity).
Synonyms: TMEM226; TMEM8C; MYOMAKER
Tractability: Antibody: its Gene Ontology location is reachable by antibodies, with high confidence; UniProt places it where antibodies can reach, with medium confidence; UniProt predicts a signal peptide or a membrane-spanning region.
Gene: Protein-coding gene on chromosome 9 (133,514,586 to 133,528,612, reverse strand). Ensembl gene ENSG00000187616.
Subcellular location: Cell membrane; Golgi apparatus membrane
Gene Ontology:
Biological process: myoblast fusion; positive regulation of skeletal muscle hypertrophy
Cellular component: plasma membrane; Golgi membrane; membrane
Genetic constraint (gnomAD): Loss-of-function variants: 12 observed, 19.07 expected, observed/expected ratio (o/e) 0.63, 90% interval 0.4 to 1.02. The upper end of that interval is the gene's LOEUF score, 1.02, which puts it in group 4 of 6, group 1 being the genes least tolerant of losing a copy. Missense variants: 197 observed, 246.16 expected, observed/expected ratio (o/e) 0.8, 90% interval 0.71 to 0.9. Synonymous variants: 101 observed, 105.62 expected, observed/expected ratio (o/e) 0.96, 90% interval 0.81 to 1.13.
Homologues: Orthologues: chimpanzee MYMK (99% identical), macaque MYMK (99% identical), dog MYMK (95% identical), pig MYMK (90% identical), mouse Mymk (89% identical), rat Mymk (89% identical), guinea pig MYMK (86% identical), tropical clawed frog mymk (83% identical), zebrafish mymk (75% identical). Paralogues in human: TMEM8B (31% identical), PGAP6 (30% identical).
Diseases named in the same sentence as MYMK in open-access papers:
MYMK is named in the same sentence as 8 diseases in open-access papers, as found by Europe PMC text mining. Sharing a sentence is not in itself a finding about the gene and the disease. The quoted sentences say what the papers report.
Carey-Fineman-Ziter syndrome (6 papers, 2018 to 2025). "Carey Fineman Ziter Syndrome (CFZS) is a rare autosomal recessive disease caused by mutations in the MYMK locus which encodes the protein, myomaker." (PMID 38790073, 2024). "Recently, hypomorphic variants in MYMK were shown to cause the congenital myopathy known as Carey-Fineman-Ziter syndrome (CFZS; OMIM #254940)." (PMID 35642635, 2022). "Homozygosity of this human variant resulted in a spectrum of abnormalities that mimicked the clinical presentation of Carey-Fineman-Ziter syndrome (CFZS), caused by hypomorphic MYMK variants." (PMID 35642635, 2022). "Although there are no existing animal models that mimic Carey-Fineman-Ziter syndrome resulting from MYMK mutations, mutations in DYSF, the gene responsible for heterogenous limb-girdle muscular dystrophy type 2B (LGMD2B), results in myoblast fusion deficiency." (PMID 36400788, 2022).
cryptorchidism (1 paper, 2018). The failure of one or both testes of a male fetus to descend from the abdomen into the scrotum during the late part of pregnancy. "Pierre Robin sequence and cryptorchidism (in males) are consistent features described in association with MYMK mutations, and both may be a consequence of muscle dysfunction in early development." (PMID 29560417, 2018).
muscular dystrophies (1 paper, 2018). "Mainly proximal myopathy places MYMK-associated CFZS in the differential diagnosis for the limb-girdle muscular dystrophies." (PMID 29560417, 2018).
myopathy (3 papers, 2018 to 2022). A disease of the muscle in which the muscle fibers do not function properly. "MYOMAKER (MYMK) and MYOMIXER (MYMX) are proteins that harbor fusogenic activity and mutations in MYMK and MYMX result in a clinical myopathy known as Carey-Fineman-Ziter syndrome." (PMID 36400788, 2022). "Diagnostic trio-exome sequencing of the affected patients did not identify any known pathogenic variants in myopathy-related genes, including MYMK." (PMID 35642635, 2022).
MYMK also shares sentences with these, for which no sentence is quoted: congenital fibrosis of the extraocular muscles (1 paper); facial weakness (1); limb-girdle muscular dystrophy type 2B (1); weakness (1).